JPX (JPX transcript, XIST activator)
Diseases named in the same sentence as JPX in open-access papers (continued):
Sharing a sentence is not in itself a finding about the gene and the disease.
lung adenocarcinoma (1 paper, 2024). A carcinoma that arises from the lung and is characterized by the presence of malignant glandular epithelial cells. "In this experimental work, we unveiled a novel competing endogenous RNA network (ceRNET) involving the lncRNA JPX, miR-378a-3p, and its downstream oncogenic targets in lung adenocarcinoma cells." (PMID 38672608, 2024). "We downloaded and analyzed the sequencing data of GSE19188 and GSE33532 datasets from R2 and found that JPX was significantly upregulated in lung adenocarcinoma tissues in comparison to normal lungs, with a fold change of 1.45 (p = 0.0001) and 1.21 (p = 0.0103), respectively." (PMID 38672608, 2024).
melanoma (1 paper, 2025). A malignant, usually aggressive tumor composed of atypical, neoplastic melanocytes. "LncRNA JPX interacts with and destabilizes YTHDF2 to facilitate melanoma progression." (PMID 41145465, 2025).
ovarian tumors (1 paper, 2024). "Downregulation of XIST in ovarian tumors is associated with reduced expression of upstream activators JPX and FTX." (PMID 39546568, 2024). "We also found that XIST downregulation was associated with lower levels of its activators, JPX and FTX, in ovarian tumors." (PMID 39546568, 2024).
schizophrenia (1 paper, 2024). A major psychotic disorder characterized by abnormalities in the perception or expression of reality. "Additionally, enhancers from female-specific TRDs were found to regulate two genes known to escape XCI, (XIST and JPX), underlying the importance of TRDs in deciphering sex differences in schizophrenia." (PMID 38645177, 2024).
tumor (17 papers, 2017 to 2025). "The best-known role of JPX is that it serves as a molecular switch in the X chromosome inactivation in females, but studies also show that it is implicated in different cancers and can act as an oncogene in certain cases while as a tumor suppressor in others." (PMID 33168013, 2020). "Then, the oncogenic activity of JPX, the tumor-suppressive role of miR-378a-3p, and the contribution of their functional interaction to cancer hallmarks were demonstrated using assays for cell proliferation, migration, invasion, and 3D-spheroid formation." (PMID 38672608, 2024). "First, a reverse expression pattern of JPX and miR-378a-3p was found in tumor tissues compared to normal lungs; subsequently, physical interaction between the molecules was demonstrated." (PMID 38672608, 2024). "Our analyses on two small patient cohorts and the larger one of the TCGA gave consistent results, showing an overexpression of JPX in tumor tissues in comparison to normal lungs, as expected for an oncogene." (PMID 38672608, 2024). "Consistent with the results in vitro, overexpression of JPX significantly increased tumor volume and tumor weight compared with those in the control group." (PMID 35681693, 2022). "The tumor xenograft assay in nude mice was performed to demonstrate the role of the JPX/miR-25-3p/SOX4 axis in CC." (PMID 32943989, 2020). "Functionally, JPX promoted cell proliferation, migration, and invasion and facilitated tumor growth in xenograft mouse model." (PMID 31941509, 2020). "In the xenograft tumor mice, RT-qPCR showed that JPX expression was remarkably upregulated in tumor tissues." (PMID 31941509, 2020). "In particular, miR-378a negatively impacted the ability of tumor cells to form anchorage-independent aggregations; however, that ability was recovered when JPX was also overexpressed, again pointing towards the functional relationship between the lncRNA and the miRNA." (PMID 38672608, 2024). "Moreover, JPX overexpression induced an increase in Twist1 expression in tumor tissues at the RNA and protein levels." (PMID 31941509, 2020). "In addition, knockdown of JPX was found to inhibit HeLa cell viability and tumor development via up-regulating the expression of miR-25-3p and inhibiting the expression of SOX4." (PMID 32943989, 2020). "Thus, in LUAD cell models, an array of biological assays were performed to evaluate the potential oncogenic activity of JPX, the potential tumor-suppressive role of the miRNA, and the contribution of the putative functional interaction of JPX/miR-378a to cancer hallmarks." (PMID 38672608, 2024). "Moreover, downregulated expression of JPX decreased tumor size and tumor cell proliferation." (PMID 32943989, 2020). "We found upregulation of JPX promoted ESCC cell proliferation, migration, and invasion in vitro and tumor growth in vivo." (PMID 35681693, 2022). "It has also been shown that JPX is lowly expressed in HCC and inhibits HepG2 cell growth or tumorigenesis in a XIST-dependent manner, revealing that JPX has a tumor-suppressing effect in HCC." (PMID 31941509, 2020). "Inhibition of JPX/FTX transmits the signal to XIST, decreasing its expression levels and completing the sequence that ultimately leads to both activation of tumor growth and stimulation of metastatic capacity." (PMID 33053887, 2020). "MEG3, JPX, RNCR3, and ZFAS1 showed significant decrease with tumour malignant progression." (PMID 29138748, 2017). "To further assess the relevance of JPX and Twist1, we divided the lung cancerous specimens into two groups: the “JPX high” and “JPX low” groups, which had higher or lower JPX expression, respectively, in tumor tissues than that in the paired adjacent non-tumor tissues." (PMID 31941509, 2020).
cancer (12 papers, 2016 to 2025). A tumor composed of atypical neoplastic, often pleomorphic cells that invade other tissues. "JPX is involved with cancer growth, metastasis, and chemoresistance, also by acting as a competing endogenous RNA for microRNA, interacting with proteins, and regulating some specific signaling pathways." (PMID 41440381, 2025). "Some studies demonstrated that JPX overexpression was able to prompt cancer hallmarks in cell culture." (PMID 38672608, 2024). "Consistently, upregulation of JPX has been demonstrated to expedite cancer cell proliferation, invasion, and metastasis in a variety of cancer types." (PMID 35681693, 2022). "A large number of studies have shown that JPX is abnormally expressed in a variety of malignancies, and it acts oncogenic regulator or suppressor relying on the cancer types." (PMID 35681693, 2022). "AC10889.1, TTTY15, XIST, AC006157.1, PAX8-AS1, SNHG25, and JPX were mainly involved in cancer development." (PMID 33924951, 2021). "The cancer promoting effect of lncRNA SNHG1 and JPX in cancer has been validated." (PMID 39716349, 2025). "LncRNA JPX acts as an oncogenic regulator in various types of cancer." (PMID 35681693, 2022). "Thus, we hypothesized that lncRNA JPX might be related to the development of OS and participate in the melatonin‐mediated anti‐cancer effects in OS cells." (PMID 34547170, 2021). "LncRNA LUADT1, ZDHHC8P1, JPX, LINP1 and AGAP2‐AS1 have been reported to participate in the development of cancers." (PMID 34547170, 2021). "For example, the lncRNA JPX, the TFs MYC and E2F1 and the miRNA let-7 play crucial roles in human cancers." (PMID 27322142, 2016).
adenocarcinoma (1 paper, 2024). A common cancer characterized by the presence of malignant glandular cells. "Analyses of three different datasets revealed that the lncRNA JPX was overexpressed in adenocarcinoma tissues in comparison to normal lungs, as expected for an oncogene." (PMID 38672608, 2024).
JPX also shares sentences with these, for which no sentence is quoted: colorectal cancer (2 papers); gastric cancer (2); osteosarcoma (2); allergic asthma (1); allergic rhinitis (1); asthma (1); colorectal tumors (1); head and neck squamous cell carcinoma (1); prostate carcinoma (1); uveal melanoma (1).